INS (insulin)
Diseases named in the same sentence as INS in open-access papers (continued):
Sharing a sentence is not in itself a finding about the gene and the disease.
Hyperglycemia (continued). "Genetic defects in pancreatic β-cell functioning (known as maturity-onset diabetes of the young, MODY) is caused by genetic mutation or defect in a single gene in different chromosomes in an autosomal dominant manner leading to insufficient insulin production and hyperglycemia." (PMID 34564146, 2021). "Insulin treatment might not have had a sufficient effect on glucose concentrations or was introduced late, as reflected by the longer duration of exposure to hyperglycaemia in insulin-treated infants." (PMID 33863775, 2021). "Therefore, our data support a model that heparin binds with insulin to reduce the skeletal muscle glucose uptake and by doing so, induces hyperglycaemia and glucose homeostasis abnormalities." (PMID 34277977, 2021). "Moreover, hyperglycemia in NIDDM is a hazardous issue that disturbs the genetic expression responsible for insulin secretion, e.g., sirtuin-1 (Sirt-1) and glucose transporter-2 (GLUT-2), in β-cells." (PMID 34833928, 2021). "All patients received 0.02–0.25 units/kg/h of regular insulin for hyperglycemia post-operatively." (PMID 33003354, 2020). "The slowing of gastric emptying may be more important than insulin secretion in regulating post-prandial hyperglycemia by limiting the amount of post-prandial glucose presented to the beta cell." (PMID 32308645, 2020). "Thus, it is unlikely that ICI 118,551 inhibits hyperglycemia induced by l-sulpiride through glucagon and insulin secretion." (PMID 33339892, 2020). "It is proven that hyperglycaemia, deficiency or absence of circulating insulin and/or C-peptide can affect body homoeostasis interfering in the development and progression of complications induced by hyperglycaemia." (PMID 31963760, 2020). "The principal finding of this study is that Dula improved GC-induced hyperglycemia during inpatient care and was associated with a lower injection frequency and insulin dose than observed in patients not treated with Dula." (PMID 32381085, 2020). "Therefore, careful diagnosis of hyperglycemia during pregnancy is crucial and all efforts should be directed toward studies on effective and safe interventions which regulate maternal insulin secretion." (PMID 32933073, 2020). "Treatments to reduce hyperglycemia and reestablish normal insulin signaling are much sought after." (PMID 31378829, 2020). "Hence disruption of the IR-Akt transduction pathway resists insulin action and results in unrestrained hyperglycemia and adipose lipolysis." (PMID 32128655, 2020). "Furthermore, the therapeutic potential of miR-206 in settings of hyperglycaemia has been reported, elucidating mechanistic roles in the inhibition of glucose production and lipogenesis and promotion of insulin signalling." (PMID 31969632, 2020). "Vaccination of IAPP transgenic mice against amyloidogenic aggregates of IAPP prevented the formation of IAPP aggregates in pancreatic islets in vivo, delayed the onset of amyloid-induced hyperglycemia and reduced local inflammation while restoring insulin production." (PMID 32131431, 2020). "We hypothesized that the consumption of acid hydrolyzed silk peptides (SPs) alleviates hyperglycemia by improving insulin sensitivity and subsequently normalizing glucose-stimulated insulin secretion in T2DM." (PMID 31991596, 2020). "β-Blockers may also contribute to the development of hyperglycemia by diminishing the release of insulin from pancreatic β-cells." (PMID 32983560, 2020). "This study suggests that Dula could provide glycemic control while reducing the insulin dose and injection frequency required during the inpatient care of patients with GC-induced hyperglycemia." (PMID 32381085, 2020). "The degradation of insulin, which is made and secreted in the pancreas, by GelE would likely result in similar hyperglycemia, and a reduction in pancreatic peptides might allow for increased food intake." (PMID 32051237, 2020).
Hyperglycemia (continued). "The higher correlation of hepatic steatosis with the hyperglycemia than with the hyperinsulinemia may indicate that the carbohydrate abundance affected steatosis both directly and indirectly via insulin signalling." (PMID 32699301, 2020). "We investigated whether a long-acting glucagon-like peptide-1 receptor agonist, dulaglutide (Dula), safely improved GC-induced hyperglycemia in inpatients, to reduce insulin injection frequency." (PMID 32381085, 2020). "In this study, we proved that the extracts of D. fimbriatum (DFEs) could increase the level of insulin and alleviate hyperglycemia in diabetic rats." (PMID 31790971, 2020). "Briefly, the impaired insulin action in an insulin-resistant state promotes endogenous glucose production by the liver and limits glucose uptake by peripheral tissues (adipose tissue and muscle) resulting in hyperglycemia and compensatory hyperinsulinemia." (PMID 33266488, 2020). "Intriguingly, chronic i.c.v. leptin injection did not reverse hyperglycemia in insulin-deficient RIP-CreΔLEPR mice, suggesting that LEPRs in RIP-Cre25Mgn neurons play a critical role in glucose-lowering effects of leptin in an insulin-independent manner." (PMID 33071988, 2020). "Leptin administration into the brain combined with acipimox, which lowers blood lipids by suppressing triglyceride lipase activity, can restore normal glycemia in insulin-deficient RIP-CreΔLEPR mice, suggesting that excess circulating lipids are a driving-force of hyperglycemia in these mice." (PMID 33071988, 2020). "In T2D, insulin secretion and insulin sensitivity may be impaired, eventually leading to hyperglycemia." (PMID 33905469, 2020). "This can be explained by the fact that hyperglycemia in the HFD group could signal to β cells that more insulin was needed, so compensation could occur, including functional as well as enhanced β cell proliferation." (PMID 32607287, 2020). "Initially, insulin-producing β cells in the pancreas meet this demand but ongoing insulin resistance and ectopic lipid deposition in the pancreas itself can ultimately lead to β cell failure, hyperglycaemia, and T2D." (PMID 33233816, 2020). "IV dextrose infusion initiated at 24 hpi induced severe hyperglycemia by 48 hpi with a concurrent increase in plasma insulin; the heightened circulating insulin levels paired with unresolved hyperglycemia is consistent with peripheral insulin resistance." (PMID 32977395, 2020). "The reduced acute insulin response is the major reason for postprandial hyperglycemia." (PMID 32775460, 2020). "Furthermore, the excessive basal insulin dose can cause the necessity of CHO intake to avoid hypoglycaemia, with a consequent hyperglycaemia." (PMID 32318639, 2020). "Postprandial hyperglycemia depends on a number of factors including timing, quantity, and composition of the meal, the total amount of carbohydrate, the rate and degree of glucose absorption, the secretion of insulin, and inhibition of glucagon." (PMID 33322540, 2020). "Thus, in addition to hyperglycemia, high FFA levels caused by insufficient insulin action represent a potential pathogenic factor in diabetic complications." (PMID 33150239, 2020). "Restoration of adipsin to diabetic mice ameliorated hyperglycemia by augmenting insulin secretion." (PMID 32079203, 2020). "This suggests that combining a GLP‐1RA with conventional insulin therapy might prevent both hyperglycemia and hypoglycemia, and thus achieve more ideal glycemic control." (PMID 31168938, 2020). "However, as insulin release capacity remains high throughout life and hyperglycemia is reduced after 6 months of age, the ob/ob mouse model is probably not the best study model to cover all manifests of T2DM in humans." (PMID 32655492, 2020).
Hyperglycemia (continued). "Insulin alone is capable of this action; thus, the unique role of this hormone in the regulation of peripheral glucose uptake during hyperglycemia represents a bottleneck in the physiology of whole body glucose disposal and in the pharmacological approaches to improve its dysregulation." (PMID 31996711, 2020). "Antidiabetic drugs for T2DM can directly target hyperglycemia by promoting insulin release from beta cells in the early stages of the disease by improving insulin sensitivity of target cells through various pathways, or by slowing down carbohydrate digestion after a meal." (PMID 33396883, 2020). "When pancreatic beta cells fail to meet the increased insulin demand, hyperglycemia develops." (PMID 33178196, 2020). "Combined with the results above, our data implied that DFE administration could significantly increase the insulin concentration and lower the blood glucose level in the diabetic rats, which may thereby alleviate hyperglycemia." (PMID 31790971, 2020). "GCK mutations cause a resetting of the glucose and is associated with mild hyperglycemia and low ranges of HbA1c (less than 7.6%), while the secretion and regulation of insulin is not completely altered." (PMID 31956423, 2020). "Our findings, therefore, suggest that the failure of a majority of β cells to compensate for prevailing insulin needs might portend the eventual development of hyperglycemia/T2D." (PMID 33353164, 2020). "For example, if the expression of the insulin is too low, the hyperglycemia remained." (PMID 33202992, 2020). "Although the link between hyperglycaemia and insulin deficiency has been examined in detail in diabetic patients, the impairing impacts of the excess level of insulin are not well acknowledged." (PMID 33145961, 2020). "Insulin secretion in response to hyperglycemia (~18 mM) is blunted in Irp2−/− mice." (PMID 31941883, 2020). "Gender differences in reported hyperglycemia among insulin users also greatly referred to women." (PMID 33067519, 2020). "In addition, after implantation into DM patients or immunodeficient diabetic animals, these in vitro-generated IPCs or islet organoids should respond to changing blood glucose and produce sufficient insulin and finally reverse hyperglycemia." (PMID 32641151, 2020). "The objective of the present study was to explore the long-term postpartum glucose metabolism in women with previous GDM, and study the mechanism of hyperglycemia from gestation to postpartum by investigating the postpartum insulin resistance and insulin secretion." (PMID 32184821, 2020). "Moreover, there are ongoing clinical trials assessing the efficacy of early management of hyperglycemia with basal insulin (NCT01683331) and sitagliptin (NCT01928199) for the prevention of PTDM." (PMID 32368254, 2020). "Failure to do this could make uneven concentrations of insulin that may possibly lead to hypo- or hyperglycemia." (PMID 33046046, 2020). "However, susceptible pregnant women are unable to compensate for insulin resistance and will develop hyperglycemia due to insufficient insulin secretion secondary to pancreatic β-cell dysfunction." (PMID 32500037, 2020). "Insulin production and sensitivity are preserved in patients with iatrogenic hyperglycemia." (PMID 33261643, 2020). "In addition to reducing hyperglycemia and enhancing insulin sensitivity, it has been suggested that metformin improves endothelial function and promotes vasoprotection." (PMID 32467714, 2020). "These systems are not able to increase insulin infusion in response to elevated serum glucose, but reduce hypoglycemic episodes without causing rebound hyperglycemia." (PMID 33332410, 2020). "The results show that hyperglycemia and impaired glucose tolerance are reversible and could be normalized by insulin administration." (PMID 32699230, 2020). "A substitute insulin injection therapy is desired in patients with GC-induced hyperglycemia." (PMID 32381085, 2020).
Hyperglycemia (continued). "The symptoms were reversed after using insulin to treat hyperglycaemia." (PMID 32019775, 2020). "Since Kuma mice begin to reveal hyperglycemia from 4-week-old, we then isolated pancreatic islet whole cell lysates from 3- and 7-week-old WT and Kuma mice and performed western blot analysis to detect insulin." (PMID 32699230, 2020). "Insulin sensitivity of peripheral tissues is critical for preventing hyperglycemia after meals." (PMID 33043040, 2020). "Hyperglycemia of the mutant can be rescued by insulin administration." (PMID 32699230, 2020). "After transplantation to immunodeficient diabetic mice, these cells could secrete human insulin and reverse hyperglycemia." (PMID 32430053, 2020). "Measurements of brain-to-plasma glucose concentrations in vivo have not confirmed a substantial degree of BBB leakage in streptozotocin-induced diabetic rats maintained under hyperglycemia (>20 mmol/L) for 1 month, or in insulin resistant GK rats that show sustained fed glycemia of 9–16 mmol/L." (PMID 32265637, 2020). "Antidiabetic agents like GLP-1 analogues or SGLT-2 inhibitors are promising alternatives to insulin as they have low risk for hypoglycemia, but the experience in GC-induced hyperglycemia is small, and again, outcome studies are lacking." (PMID 33348743, 2020). "Our data suggest that glucagon signaling does not drive hyperglycemia in insulin-deficient mice lacking LEPRs in RIP-Cre25Mgn administered i.c.v. leptin." (PMID 33071988, 2020). "PRS adjusted for PS with or without exogenous insulin infusion was significantly associated with hyperglycemia occurrence in the neohepatic phase." (PMID 33301501, 2020). "Deleterious effects of T1D on the immunological system have been observed before, and studies have associated it with the relative absence of insulin rather than hyperglycemia onset." (PMID 33312173, 2020). "These multiple effects of liraglutide on β-cells might have contributed to the increased β-cell numbers, recovering insulin secretion, and ameliorating the hyperglycemia observed in the current study." (PMID 32785012, 2020). "This eventually leads to a state of insulin depletion and hyperglycemia by young adulthood." (PMID 32977673, 2020). "Importantly, chronic hyperglycaemia causes the abrogated expression of GPR40 and the downregulated release of insulin." (PMID 32917053, 2020). "In poorly controlled DM, infection-related hyperglycemia is exacerbated, leading to aggressive insulin treatment, significant blood glucose fluctuations and potentially to ketosis; hyperglycemic emergencies can therefore be the initial clinical presentation of COVID-19 in these patients." (PMID 32708504, 2020). "In addition, in the present study, we investigated the effect of different glycemic level (i.e., normoglycemia, mild hyperglycemia, and restored euglycemia following long term in vivo insulin treatment) on the vulnerability to AF induction." (PMID 32903422, 2020). "Therefore, the significant effect of O. indicum extract to inhibit BSA glycation as reported by Singh and Kakkar can be a boon in anti-hyperglycemia management by protecting beta cells and improving insulin sensitivity." (PMID 33276419, 2020). "Furthermore, oxidative stress, hyperglycemia, dyslipidemia, and resistance to insulin can give rise to mitochondrial dysfunction." (PMID 33166296, 2020). "Acutely unwell patients in hospital may need to stop using IDegAsp and be switched to a basal-bolus insulin regimen to prevent hyperglycaemia." (PMID 32290465, 2020). "Genetic deletion of UCP-2 in mice enhances islet ATP generation and insulin secretion during glucose stimulation and reduces hyperglycemia in the ob/ob mice (a well-known diabetes type 2 mouse model), providing further support for the role of UCP-2 in the pathogenesis of the disease." (PMID 32528413, 2020). "If hyperglycemia remains uncontrolled by these combinations, establishing insulin therapy together with maintained metformin treatment may be necessary." (PMID 31313243, 2020).
Hyperglycemia (continued). "In most cases, the insulin was titrated to achieve and maintain hyperglycemia ~20 mmol/L." (PMID 33419247, 2020). "The down regulation of GLUT2 in the liver in fowls may be a compensatory mechanism to prevent further utilization of glucose in the liver during insulin-induced hypoglycemia that sustains hyperglycemia even in a fasting state." (PMID 32317707, 2020). "Looking into PT level for each drug class, majorities of AEs with substantial disparity in reporting rate between genders were dominated by women, including urinary tract and genital infection after SGLT2i treatment, edema after TZD treatment, hyperglycemia in insulin users, and UTI in DPP-4i users." (PMID 33067519, 2020). "These mice also had greater amounts of urine glucose, which might play an important role in protecting the mice from developing hyperglycemia despite the reduced production of insulin from the β-cells." (PMID 32877990, 2020). "In this group of pregnant women, hyperglycemia lasted on average 1.69 ± 0.89 days and 12.25 ± 11.28 insulin units/day were administered, resulting in fasting glucose levels of 121.9 ± 21.9 mg/dL, 130.9 ± 22.4 mg/dL premeal, and 165.2 ± 24.6 mg/dL one-hour postprandially." (PMID 32079162, 2020). "The explanation may be that hyperglycemia stimulates insulin which serves as a growth hormone for the fetus during pregnancy and excessive weight gain may result in an overproduction of insulin." (PMID 32527333, 2020). "All these functions are important in prescribing complex tasks, such as aligning the insulin dose with the carbohydrate content, predicting the impact of physical activity on blood glucose, or even recognizing and treating hypoglycaemia and hyperglycaemia appropriately." (PMID 32005901, 2020). "Thus, a substitute for insulin injection therapy is desirable in patients with GC-induced hyperglycemia." (PMID 32381085, 2020). "The presence of insulin therapy may be considered per se a marker of advanced stages of disease, which are more likely to be characterized by hyperglycemia and endothelial cell dysfunction." (PMID 32471222, 2020). "Chronic hyperglycemia leads to a defect in insulin production due to glucotoxicity." (PMID 32059692, 2020). "A non-ketotic hyperglycemia-associated occipital lobe seizure can manifest itself as color flashes, blurry vision with periodic confusion, and usually resolves with insulin treatment and rehydration." (PMID 32656040, 2020). "The onset of the action on hyperglycemia started at 1 h for the oral nano-insulin formulation, which could be due to the required transport time for insulin-loaded particles to reach the blood stream." (PMID 32751231, 2020). "Likewise, a recent study indicated that efferent vagal stimulation attenuates hyperglycemia in endotoxemia by inducing insulin in fasted mice." (PMID 32471438, 2020). "Insulin may lose its cardioprotective effects due to an impairment of MAPK phosphatase-1 expression or because hyperglycemia directly impairs insulin signaling." (PMID 32326182, 2020). "Adding low doses of insulin avoids these alterations even with persistent hyperglycemia." (PMID 32430795, 2020). "Age-related insulin- sensitivity decline, accompanied by hyperglycemia, might disequilibrate glucose homeostasis, possibly triggering a potential onset of T2DM." (PMID 33223509, 2020). "We collected the usage of insulin with PN to indirectly monitor the prevalence of hyperglycemia." (PMID 32236124, 2020). "In this context, high insulin levels fail to control hyperglycemia." (PMID 31992349, 2020). "Therefore, Dula administration is suggested to effectively counteract these GC actions and GC-induced hyperglycemia, contributing to lower insulin injection frequency." (PMID 32381085, 2020). "But chronic hyperglycemia will eventually result in β cell exhaustion, the reversal of β cell structural adaptations evident by hypoplasia, hypotrophy, reduced proliferation, and dedifferentiation, all resulting in insulin hyposecretion." (PMID 33250773, 2020).